NOTCH1 (notch receptor 1)
Diseases named in the same sentence as NOTCH1 in open-access papers (continued):
Sharing a sentence is not in itself a finding about the gene and the disease.
glioma (continued). "miR-139-5p was identified as a tumour suppressor by negatively targeting Notch1, and this work suggests a possible molecular mechanism of the miR-139/Notch1/EMT axis for glioma treatment." (PMID 30170559, 2018). "Both shRNA1 and shRNA2 reduced Notch1 expression in glioma cells compared with control as assessed using both real-time PCR and western blotting." (PMID 29410396, 2018). "In this study, we attempted to investigate the expression and functions of Notch1 in gliomas and its relationship with miR-139-5p." (PMID 30170559, 2018). "In Grade III-IV tissues, Notch1 was higher than that in low grade gliomas (WHO II) or normal brain tissues (P < 0.05)." (PMID 30170559, 2018). "We investigate the expression of Notch-1, OPN and vascular endothelial growth factor (VEGF) associated to the stemness markers nestin and CD133 in three stages of murine gliomas induced by N-ethyl-N-nitrosourea (ENU)." (PMID 30140373, 2018). "Notch1 expression was measured using an immunohistochemical analysis in 29 different grades of glioma tissues and 4 normal brain tissues." (PMID 30170559, 2018). "Notch1 knockdown also increased Ed-dUTP labeling in glioma cells, which indicated that DNA fragmentation was induced during the apoptotic process (P < 0.05)." (PMID 29410396, 2018). "The results of the heat map showed 20 differentially expressed genes (DEGs) including 10 upregulated genes and 10 downregulated genes, of which NOTCH1 was remarkably overexpressed in glioma tissues in comparison with adjacent normal tissues." (PMID 30072869, 2018). "The qRT-PCR results suggested that NOTCH1 was overexpressed in glioma cells compared with the HA1800 cell line, especially in U87 cells (P < 0.01)." (PMID 30072869, 2018). "Our results revealed that Notch1 was responsible for the excessive proliferation and reduced apoptosis of glioma cells." (PMID 29410396, 2018). "MiR-139-5p overexpression partially phenocopied Notch1 siRNA, whereas the forced expression of Notch1 reversed the effects of miR-139-5p on the invasion of glioma." (PMID 30170559, 2018). "NOTCH1 functions as a tumour suppressor gene in HNSCC39 and is implicated in the radioresistance of glioma stem cells." (PMID 29374236, 2018). "In this article, we validated Notch1 expression in GBMs on four gene expression profiling cohorts of gliomas." (PMID 29410396, 2018). "Notch-1 is a transmembrane receptor involved in cell-cell signalling that has been related to glioma survival and proliferation." (PMID 30140373, 2018). "Recently, several studies have reported the expression features of Notch1 in gliomas with different results regarding tumor progression and prognosis." (PMID 29410396, 2018). "It has been demonstrated that the knockdown of Notch-1 or the inhibition of its activity in glioma cell lines led to cell cycle arrest, accompanied by decreased cell proliferation and increased cell death." (PMID 29857516, 2018). "Our studies and others have shown that inhibition or downregulation of Notch1 sensitized glioma cells to irradiation." (PMID 29152141, 2017). "In recent years, the Notch1 signaling in proliferation of gliomas for the survival is increasingly concerned." (PMID 28950865, 2017). "We examined Notch1 expression in 69 glioma tissue specimens and 8 normal brain tissues pecimens by immunohistochemistry." (PMID 29152141, 2017). "More importantly, we show that Fringe can modulate the glioma cell fate decisions by regulating the Notch1 signaling, i.e., realizing the transition of grades III ∼ IV to grades I ∼ II, and then to normal brain tissue." (PMID 28950865, 2017). "First, up-regulation of miR-145 and knockdown of BNIP3 decreased the protein expression of Notch1, Hes1, and p21 in glioma cells." (PMID 28977881, 2017).
glioma (continued). "To date, it has been shown that Notch1 and its ligands, Dll1 and Jag1, are overexpressed in many glioma cell lines and primary human gliomas." (PMID 28950865, 2017). "Second, down-regulation of miR-145 and up-regulation of BNIP3 increased the protein expression of Notch1, Hes1, and p21 in glioma cells." (PMID 28977881, 2017). "It has been shown that Notch1 and its ligands, Dll1 and Jag1, are overexpressed in many glioma cell lines and primary human gliomas." (PMID 28950865, 2017). "Our results confirmed that the regulation between Notch1, its ligands, and Fringe can modulate the glioma cell fate decisions." (PMID 28950865, 2017). "Immuno-histochemistry of a primary human glioma tissue array shows the presence in the nucleus of the Notch1 intracellular domain, indicating Notch1 activation in situ." (PMID 28950865, 2017). "The roles of Notch1 in some cancers have been firmly established, and recent data implicate that it plays important roles in glioma cell fate decisions." (PMID 28950865, 2017). "A suppressive role Notch1 has also been reported in several cancer types such as skin cancer, myeloid leukemia and glioma." (PMID 29152141, 2017). "A crosstalk between inflammatory mediators and Notch1 has been evidenced in colon cancer, glioma, cholangiocarcinoma and in macrophages activation." (PMID 28157712, 2017). "Although our model provides a new theoretical framework to investigate the effects of Dll1, Jag1 and Fringe in the Notch1 signaling system in glioma cells, it ignores the spatial effects which can be also important." (PMID 28950865, 2017). "Other research groups reported that knockdown of Notch1 expression by siRNA in U251 glioma cells downregulated the expression of EGFR, indicating the crosstalk and interaction of Notch1 and EGFR signaling pathways." (PMID 28157712, 2017). "Down-regulation of Notch1, Dll1, or Jag1 by RNA interference induces apoptosis and inhibits proliferation in multiple glioma cell lines." (PMID 28950865, 2017). "In glioma, expressions of the constitutively active intracellular domains of Notch1 or Notch2 protect glioma stem cells against radiation." (PMID 28038467, 2017). "In glioma and medulloblastoma, miR-34a levels were lower than in normal brain tissue, which in turn directly bound to Notch1 and Notch2 3’-UTR and suppressed Notch1 and Notch2 expression." (PMID 29299142, 2017). "MiR-129 induced autophagy through mTOR signaling by targetedly suppressing Notch-1 in glioma cell lines." (PMID 26824182, 2016). "In an effort to elucidate the underlying molecular mechanism of miR-92a-3p in glioma cells and GSCs, we applied bioinformatics and predicted that CDH1 and Notch-1 are the potential target genes of miR-92a-3p." (PMID 27801803, 2016). "In line with previous studies, we confirmed that knockdown of Notch-1 induced autophagy in glioma cells." (PMID 26824182, 2016). "Inhibition of NOTCH1 pathway has been shown to sensitize cancer cells to chemotherapy in prostate cancer, ovarian cancer, colon cancer, and glioma." (PMID 26528858, 2016). "Subsequent mechanistic investigation indicated that cadherin 1 (CDH1)/β-catenin signaling and Notch-1/Akt signaling were the downstream pathways of miR-92a-3p in glioma cells and GSCs, respectively." (PMID 27801803, 2016). "Notch1 and Hes1 have been demonstrated to be important oncogenes playing critical roles in glioma cell survival and TMZ resistance." (PMID 27894350, 2016). "In conclusion, these findings identify a new function for miR-129 as a potent inducer of autophagy through a novel Notch-1/E2F7/Beclin-1 axis in glioma." (PMID 26824182, 2016). "Collectively, these data demonstrated that miR-92a-3p targeted CDH1/β-catenin and Notch-1/Akt signaling pathways in glioma cells and GSCs, respectively." (PMID 27801803, 2016). "Notch1, through regulation of PI3K/Akt activity and Mcl-1, has been implicated in the radioresistance of glioma initiating cells." (PMID 26716508, 2016).
glioma (continued). "In this study, the major novel findings were that miR-129 is a new inducer of autophagy both through mTOR signaling and upregulation of Beclin-1 by targetedly suppressing Notch-1 in glioma cell lines." (PMID 26824182, 2016). "Mechanically, we demonstrated that miR-92a-3p targeted CDH1/β-catenin signaling in glioma cells, while Notch-1/Akt signaling was the downstream pathway of miR-92a-3p in GSCs." (PMID 27801803, 2016). "It has been demonstrated that Notch-1 promoted proliferation and survival of glioma cells through EGFR/Mcl-1 and mTOR signaling." (PMID 26824182, 2016). "Our studies now demonstrate for the first time that MDA-9 promotes glioma stem cell phenotypes and survival through regulation of NOTCH1, C-Myc, STAT3 and Nanog in GSCs." (PMID 27472461, 2016). "For example, miR-34 family inhibited Notch1 and Notch2 levels in glioma and gastric cancer cells and suppressed self-renewal of pancreatic cancer stem cells through targeting Notch1 and Notch2 receptors." (PMID 27191259, 2016). "In lower grade gliomas with IDH mutations and 1p19q co-deletion, the authors found frequent mutations in CIC, FUBP1, PI3 kinase pathway genes, NOTCH1, ZBTB20, and ARIDIA, in addition to activating TERT promoter mutations." (PMID 26244119, 2015). "The oppositely directed expression patterns of EGFR and NOTCH1 in these two syngeneic glioma cell lines were confirmed at the protein level by immunoblotting." (PMID 26307682, 2015). "Knockdown of Notch1 or Notch2 sensitized glioma stem-like cells to radiation and impaired xenograft tumor formation." (PMID 26273424, 2015). "Such inhibitory function of miR146a on gliomas has been attributed to the down-regulation of the key neural stem cell factor NOTCH1." (PMID 25986346, 2015). "By contrast, several studies have shown that Notch2 inhibits tumor cell growth by antagonizing Notch1 and that upregulation of Notch2 in U251 cells can suppress glioma cell proliferation." (PMID 25323114, 2014). "This phenotype was reversed by the overexpression of NICD of Notch1 or Notch2, confirming that Notch is essentially involved in the survival of glioma BTPCs post irradiation." (PMID 25601901, 2014). "The tumor-suppressive role of Notch1 is supported by the fact that it has been detected in all gliomas but a subset of grade IV tumors." (PMID 25601901, 2014). "To further elucidate the underlying mechanism of C6 glioma cells transdifferentiating into ECs, we evaluated the protein expression of HIF-1α, Notch1, Flk1, and p-Flk1 in glioma tissue and C6 glioma cells by Western blot." (PMID 24722469, 2014). "GSI-X treatment did not affect the invasive ability of any CSC, except for c-CSC3, although other authors report that genetic Notch1 knockdown resulted in reduced cell migration invasion in a glioma cell line by inhibition of β-catenin and NF-κB signaling." (PMID 25380967, 2014). "Equally, knocking-down Notch1 or overexpressing Notch2 suppressed cell growth and invasion in addition to enhancing apoptosis of subcutaneously engrafted U251 and A172 glioma cells." (PMID 25601901, 2014). "In vitro, the expressions of HIF-1α, Notch1, Flk1, and p-Flk1 in transdifferentiation-induced C6 glioma cells were significantly higher than the control." (PMID 24722469, 2014). "They proved that both upregulating of Notch1 and knocking down Notch2 had the effect of suppressing glioma cell growth and invasion as well as inducing apoptosis." (PMID 24053158, 2013). "In particular, we report anti-glioma effect of NOTCH3 knockdown similar to that previously reported about silencing of NOTCH1." (PMID 24143218, 2013). "Exogenous expression of Notch1 in glioma cells has been shown to increase their migratory and invasive capacity." (PMID 23688168, 2013). "For instance, siRNA targeting NOTCH1 inhibits proliferation and invasion of glioma cells and induces apoptosis in vitro and in vivo." (PMID 24143218, 2013).
glioma (continued). "Fibulin-3 promoted glioma growth by promoting Notch-1 cleavage and upregulating the active Notch-1 intracellular domain (NICD) to reduce apoptosis." (PMID 23936443, 2013). "Notch-1 and its ligands, Delta-like-1 and Jagged-1, have been shown to be overexpressed by many glioma cell lines." (PMID 22348397, 2012). "Our examination of other transcripts known to interact with miR-34a in GBM revealed that only NOTCH1 was significantly repressed by the miRNA in bona fide proneural glioma cells." (PMID 22479456, 2012). "When the expression of Notch1, Dll1 or Jagged1 was down-regulated by RNA interference, apoptosis and proliferation inhibition in multiple glioma cell lines were induced." (PMID 21342503, 2011). "Notch1 and its ligands, Dll1 and Jagged1, were overexpressed in many glioma cell lines and primary human gliomas." (PMID 21342503, 2011). "MiR-146a inhibits the gliomagenesis process, suppressing the migration and proliferation of glioma cells, in addition to its ability to restrict the formation of glioma stem cells by regulating the Notch1 pathway, reducing proliferation, and inducing apoptosis." (PMID 39795214, 2025). "Taken together, PDGF‐D increased NOTCH1 expression in glioma cells by upregulating NF‐κB p‐p65." (PMID 40530904, 2025). "Further, mutant cells reacted weakly to a lectin called Riccinus communis, which specifically binds to galactose residues compared to wild-type glioma cells, and β-1,4-GalT-V could be immunoprecipitated with Notch-1." (PMID 40869407, 2025). "Accordingly, we hypothesized that PDGF‐D can upregulate NOTCH1 in glioma cells by activating NF‐κB p65, resulting in the EMT and metastasis of glioma cells." (PMID 40530904, 2025). "Indeed, connections between TUG1 and either NOTCH1 or PD-L1 have already been described in the literature for glioma and hepatocellular carcinoma, respectively." (PMID 40407592, 2025). "The NOTCH1 gene showed a high percent of changes across all types of gliomas." (PMID 40679044, 2025). "Here, we showed that the NOTCH1 gene was highly mutated in both LGG and HGG gliomas, which may indicate that such alterations happen early and are constant throughout the stages of glioma progression." (PMID 40679044, 2025). "Furthermore, it was confirmed that Notch1 and PD‐L1 expression were localized to CAFs in glioma tissues." (PMID 40656546, 2025). "PDGF‐D promotes the invasion and migration of glioma cells by activating the NF‐κB/NOTCH1 pathway." (PMID 40530904, 2025). "PDGF‐D knockdown significantly downregulated NF‐κB p‐p65 and p‐I‐κB in the LN18 cells (p < 0.05), while overexpression of PDGF‐D increased the phosphorylation of both proteins (p < 0.05), indicating that PDGF‐D regulates NOTCH1 signaling in glioma cells through NF‐κB p‐p65." (PMID 40530904, 2025). "Besides, the colony formation assay results showed that knockout of Notch1 would enhance proliferation inhibition of gliomas by TMZ." (PMID 39544152, 2024). "In short, knockdown of Notch1 gene would make glioma sensitized to TMZ again in vitro." (PMID 39544152, 2024). "Additionally, knockout of the Notch1 gene enhanced the efficacy of TMZ in gliomas and the survival benefit of mice." (PMID 39544152, 2024). "SNHG6 regulated the progression of glioma through upregulation of Notch1, Sox2, and EMT." (PMID 38194709, 2024). "Notch1 expression is higher in high‐grade glioma compared to low‐grade glioma." (PMID 36971192, 2023). "Furthermore, STC1 can activate the Notch1 signaling pathway as an atypical ligand of the Notch1 receptor in glioma." (PMID 37004088, 2023). "Moreover, BRD4 has been found to be concentrated at the Notch1 promoter region, thus modulating the Notch1 signaling pathway that is involved in the regulation of the self-renewal and tumorigenicity of glioma stem cells." (PMID 37108181, 2023).
glioma (continued). "This is related to the promoting effects of Notch1 in the phenotype of glioma stem cells." (PMID 37284062, 2023). "JAK2/STAT3 and Notch1 signaling activation.Glioma stem marker expression." (PMID 37762011, 2023). "Conversely, over-activated Notch1 may promote differentiation and vascularization of glioma cells, which in turn accelerates their invasion and metastasis." (PMID 37322413, 2023). "Reduction in Notch1 or Notch2 levels also leads to radio-sensitive glioma stem cells." (PMID 35887547, 2022). "Additionally, constitutive expression of the active intracellular domains of Notch1 or Notch2 protects glioma stem cells against radiation." (PMID 35887547, 2022). "In glioma cells, Notch1 expression is upregulated and plays a role in tumor progression." (PMID 36180477, 2022). "A better confirmation of the role of glioma in the involvement of the NOTCH gen, is shown by analyzing the NOTCH pathway in glioma downloaded from cBioPortal for cancer genomics, highlighting that 7.4% of glioma patients show a mutation in NOTCH1 gene." (PMID 36556190, 2022). "To better understand the specific mechanism underlying the regulatory role of lncRNA FOXD2‐AS1 in glioma cells, we performed a series of assays demonstrating that lncRNA FOXD2‐AS1 upregulation led to elevated NOTCH1 expression by recruiting TAF‐1 to the NOTCH1 promoter region." (PMID 35419917, 2022). "Our findings suggest that Notch1 is a direct target gene of miR-30c in gliomas." (PMID 36180477, 2022). "However, the majority of research has focused on the importance of how Notch1-mediated signaling pathways contribute to the development, invasion, and recurrence of glioma tumors." (PMID 36382054, 2022). "Notch1 promotes glioma cell migration and invasion by stimulating β-catenin." (PMID 36006934, 2022). "Therefore, if the apoptosis of tumor cells is decreased in gliomas, the expression of Notch1 needs to be inhibited first." (PMID 36180477, 2022). "Our results suggest that miR-30c could inhibit EMT and the proliferation, migration, and invasion of glioma cells by directly acting on Notch1." (PMID 36180477, 2022). "In addition, NOTCH1 signalling pathway activation can maintain the stem cell phenotype of glioma initiating cells." (PMID 35419917, 2022). "RNAi against Notch-1 can induce cell apoptosis and inhibit the proliferation of glioma cells." (PMID 35098869, 2022). "Based on a database analysis, we predicted that Notch1, which functions as an important element in glioma, may be the direct target gene of miR-30c." (PMID 36180477, 2022). "At the same time, Notch1 was also significantly higher in patients with Grade IV glioma." (PMID 34485294, 2021). "The mRNA and protein levels of Notch1 were reduced in miR-139-overexpressing glioma cells." (PMID 34512162, 2021). "Therefore, glioma cells retain stemness and increase tumorigenicity through the transfer of Notch-1 in GSC exosomes." (PMID 34638913, 2021). "Although multi-gene combination therapy is far more effective than selective gene therapy, it still cannot completely inhibit glioma growth, and further studies are suggested.>In another study, researchers used Notch1 siRNA to reduce Notch1 function and increase Plasmid-induced Notch2 expression." (PMID 36643842, 2021). "Considering that Notch1 is a target of miR-139, we overexpressed miR-139 in glioma cells and found that miR-139 increased the expression of the host gene PDE2A and pre-miR-139, suggesting that miR-139 could amplify its own expression." (PMID 34512162, 2021). "A recent study demonstrated that both perivascular niche cells and network-forming cells of glioma could be highly resistant to radio- and chemotherapy, but these two populations were inversely regulated by Notch1." (PMID 34680255, 2021).